ZNF790 (zinc finger protein 790)
Description:
May be involved in transcriptional regulation.
Synonyms: MGC62100; FLJ20350
Tractability: PROTAC: ubiquitination databases record sites on it.
Gene: Protein-coding gene on chromosome 19 (36,816,904 to 36,850,787, reverse strand). Ensembl gene ENSG00000197863.
Subcellular location: Nucleus
Subcellular location (Human Protein Atlas): Nucleoli
Pathways (Reactome):
Gene expression (Transcription): Generic Transcription Pathway
Gene Ontology:
Molecular function: DNA-binding transcription factor activity, RNA polymerase II-specific; RNA polymerase II cis-regulatory region sequence-specific DNA binding
Biological process: regulation of transcription by RNA polymerase II; regulation of DNA-templated transcription
Cellular component: nucleus
Genetic constraint (gnomAD): Loss-of-function variants: 8 observed, 12.72 expected, observed/expected ratio (o/e) 0.63, 90% interval 0.37 to 1.13. The upper end of that interval is the gene's LOEUF score, 1.13, which puts it in group 4 of 6, group 1 being the genes least tolerant of losing a copy. Missense variants: 707 observed, 789.59 expected, observed/expected ratio (o/e) 0.9, 90% interval 0.84 to 0.95. Synonymous variants: 252 observed, 257.11 expected, observed/expected ratio (o/e) 0.98, 90% interval 0.88 to 1.09.
Homologues: Orthologues: chimpanzee ZNF345 (99% identical), macaque ZNF790 (96% identical), dog ZNF790 (84% identical). Paralogues in human: ZNF546 (45% identical), ZNF780B (44% identical), ZNF540 (43% identical), ZNF383 (43% identical), ZNF585B (43% identical), ZNF573 (43% identical), ZNF33A (42% identical), ZNF658 (42% identical), ZNF41 (42% identical), ZNF780A (42% identical), ZNF841 (42% identical), ZNF30 (42% identical), and 164 more.